PRDX1 (peroxiredoxin 1)
Diseases named in the same sentence as PRDX1 in open-access papers (continued):
Sharing a sentence is not in itself a finding about the gene and the disease.
esophageal cancer (7 papers, 2014 to 2025). A primary or metastatic malignant neoplasm involving the esophagus. "The exact role of PRDX1 in esophageal cancer, therefore, remains ambiguous, warranting further investigation." (PMID 37781072, 2023). "Recent studies indicated that the high expression of Prdx1 can promote the occurrence and progression of esophageal carcinoma and that inhibition of Prdx1 expression can promote radiation and chemotherapy sensitivity for esophageal carcinoma treatment." (PMID 32357862, 2020). "However, several lines of evidence suggest that PRDX1 may play a role as a tumour suppressor in oesophageal cancer." (PMID 27653015, 2017).
melanoma (7 papers, 2017 to 2026). A malignant, usually aggressive tumor composed of atypical, neoplastic melanocytes. "For PRDX1, histological staining revealed a loss of expression during the progression between benign nevi and malignant melanomas." (PMID 35326683, 2022). "Then, PRDX1 expression is similar to MITF in patient melanoma cells, which corroborates our in vitro data using the clones." (PMID 38790661, 2024). "PRDX1 shows significant co-expression with MITF in melanoma patients, with PRDX2 showing a tendency towards mutual exclusivity." (PMID 38790661, 2024). "The expression of PRDX1 was higher than that of PRDX2 in melanoma cells and more similar to that of MITF than that of PRDX2." (PMID 38790661, 2024). "Using data from melanoma patients, we observed that low levels of MITF expression are associated with decreased PRDX1 expression." (PMID 38790661, 2024). "On the other hand, increased expression of PRDX1 by ROS can prevent cell death and PRDX1 is involved in melanoma resistance." (PMID 38790661, 2024). "In vitro, Rb9 interacts with HSP90, an adhesion G protein, and surface peroxiredoxin 1, the result being inhibition of melanoma cells migration and invasion." (PMID 32010152, 2019). "Although PRDX1 gene variants have not been identified in human tumours, it is known that a tumorigenic human melanoma cell line, named MeWo-LC1, has a cellular phenotype identical to that of cblC patients’ cells." (PMID 34215320, 2021). "Considering that PRDX1 and PRDX2 belong to typical 2‐Cys PRDXs, and have similar active sites 8, we therefore hypothesize that PRDX1 may also play important roles in the suppression of melanoma development." (PMID 27653015, 2017). "We found PRDX1 enriched in neurons more than PRDX2, while some populations of melanoma cells express more PRDX2 than PRDX1." (PMID 38790661, 2024). "We observed that dual resistant (TDR) melanoma cell lines have higher antioxidant levels (SOD2 and PRDX1), accompanied with higher ROS levels compared to counterpart parental and dabrafenib resistant (DR) cells." (PMID 32585852, 2020). "Moreover, PRDXs are differentially expressed in patients during melanoma progression and decreased expression of PRDX1 and PRDX2 is a biomarker in melanoma compared to nevus." (PMID 38790661, 2024). "However, there are conflicting reports of the decreased expressions of PRDX1 and PRDX2 in at least a subset of melanomas." (PMID 35326683, 2022). "Based on our previous findings that antioxidants, such as SOD2 and peroxiredoxin-1 (PRDX1), are elevated in dabrafenib resistant (DR) melanoma cells identified from a proteomics screen, we aimed to assess SOD2 and PRDX1 levels in BRAF and MEK inhibitor-resistant cells." (PMID 32585852, 2020). "Our results suggested that PRDX1 and PRDX2 may play distinct roles in melanoma heterogeneity." (PMID 38790661, 2024).
colitis (6 papers, 2019 to 2025). Inflammation of the colon. "To further elucidate the pathogenic contributions of macrophages in Prdx1-mediated colitis, we depleted macrophages using clodronate liposomes (CLs)." (PMID 40715057, 2025). "The pathogenic role of Prdx1 in colitis aligns with findings in irritable bowel syndrome (IBS), where elevated serum levels of Prdx1 have been associated with disease progression." (PMID 40715057, 2025). "This suggests that PRDX1 deficiency suppressed AOM/DSS-induced colitis-associated CRC, possibly by enhancing ferroptosis, as the NRF2/GPX4 signalling pathway played a predominant role in orchestrating ferroptosis." (PMID 39430237, 2024). "Herein, we found that the number of AOM/DSS-induced colitis-associated CRC in PRDX1 knockout mice was significantly lower than that in wild-type mice, concomitant with the downregulation of NRF2 and GPX4." (PMID 39430237, 2024). "The results indicated that PRDX1 deficiency inhibited AOM/DSS-induced colitis-associated CRC." (PMID 39430237, 2024). "Furthermore, PRDX1 deficiency suppressed azoxymethane (AOM)/dextran sodium sulfate (DSS)-induced colitis-associated CRC in mice possibly by inducing ferroptosis through the NRF2/GPX4 pathway." (PMID 39430237, 2024). "Moreover, deficiency of PRDX1 attenuated AOM/DSS-induced colitis-associated CRC." (PMID 39430237, 2024). "Compared with control IgG, the Prdx1-neutralizing antibody significantly alleviated DSS-induced colitis in WT mice, as indicated by increased body weight and decreased disease activity, which were accompanied by decreased histopathological scores." (PMID 40715057, 2025). "This is supported by the reduced severity of colitis observed in Prdx1–/– mice and in mice treated with a Prdx1-neutralizing antibody." (PMID 40715057, 2025). "Overall, the elevation of circulating Prdx1 in both CD patients and mice with colitis strongly suggests its involvement in CD." (PMID 40715057, 2025). "Circulating Prdx1 exacerbates colitis in mice, whereas genetic knockout of Prdx1 or utilization of a Prdx1-neutralizing antibody markedly attenuates the development of colitis." (PMID 40715057, 2025). "Genetic knockout of Prdx1 or administration of a Prdx1-neutralizing antibody attenuated colitis in mice, as evidenced by restoration of the colonic epithelium, improved disease activity, and reduced colonic inflammation." (PMID 40715057, 2025). "In this study, we specifically explored the elevation of circulating Prdx1 in CD patients and mice with experimental colitis." (PMID 40715057, 2025). "The detection of serum Prdx1 in CD patients and mice with colitis suggests that circulating Prdx1 is pathologically relevant to intestinal inflammation." (PMID 40715057, 2025). "To address the pathological contributions of circulating Prdx1 to intestinal inflammation, we examined the impact of Prdx1 depletion on colitis using Prdx1 knockout (Prdx1–/–) mice." (PMID 40715057, 2025). "To further elucidate the pathological contributions of the NLRP3 inflammasome in Prdx1-mediated colitis, we employed the NLRP3 inhibitor MCC950 in a DSS-induced acute colitis model." (PMID 40715057, 2025). "To further validate this concept, we examined the effect of a Prdx1-neutralizing antibody on DSS-induced colitis." (PMID 40715057, 2025). "To further explore the potential association of PRDX1 expression with CRC development in vivo, we treated PRDX1-KO mice with AOM/DSS to establish the colitis-associated CRC." (PMID 39430237, 2024). "Supportively, during the process of AOM/DSS-induced colitis-associated CRC, PRDX1-KO mice were also treated with Fer-1." (PMID 39430237, 2024). "In the present study, we investigated alterations in the levels of Prdx1, -2, -4, and -6 isoforms of Prdx antioxidant enzymes after the induction of colitis and H2S donor treatment." (PMID 37237891, 2023). "Colitis reduced colonic Sod2, Gpx1, and Prdx1 (peroxiredoxin) by 37%, 29%, and 58%, respectively, compared to the non-colitic control." (PMID 31212794, 2019).
colitis (continued). "A similar increase in circulating Prdx1 is also observed in mice with experimental colitis." (PMID 40715057, 2025). "Serum Prdx1 levels were significantly increased and positively correlated with the severity of intestinal inflammation in both CD patients and mice with experimental colitis." (PMID 40715057, 2025). "To investigate whether PRDX1 promotes CRC progression by regulating tumor immune microenvironment in vivo, we treated WT and PRDX1‐KO (knockout) mice with AOM/DSS and found that the number of colitis‐associated colonic adenocarcinomas was significantly reduced in PRDX1‐KO mice compared to WT mice." (PMID 41306557, 2025). "To obtain additional evidence for a pathological role of circulating Prdx1 in colitis, we treated Prdx1–/– mice with DSS along with intravenous (i.v.)reintroduction of recombinant Prdx1 (rPrdx1)." (PMID 40715057, 2025). "Here, we found that the levels of Prdx1, -2, -4, and -6 were significantly attenuated in TNBS-induced colitis." (PMID 37237891, 2023). "In the spleen, Nfe2l2, Gclc, Gsr, Sod2, Gpx1, Gpx2, and Prdx1 were not consistently affected by T cell transfer colitis." (PMID 31212794, 2019).
head and neck squamous cell carcinoma (6 papers, 2019 to 2024). A squamous cell carcinoma that arises from any of the following anatomic sites: lip and oral cavity, nasal cavity, paranasal sinuses, pharynx, larynx, and salivary glands. "PRDX1 can promote the epithelial–mesenchymal transition in head and neck squamous cell carcinoma after entering the nucleus." (PMID 38213773, 2024). "Analysis using the tumor immune estimation resource (TIMER) demonstrated variable expression of Prdx1 in pan-cancer, with notable overexpression in head and neck squamous cell carcinoma (HNSC)." (PMID 38007535, 2023). "A long non-coding RNA, LINC00460, induced EMT, and cell proliferation and metastasis in head and neck squamous cell carcinoma via translocation of peroxiredoxin-1 into the cell nucleus." (PMID 34830941, 2021).
varicocele (6 papers, 2014 to 2025). A condition characterized by the dilated tortuous veins of the spermatic cord with a marked left-sided predominance. "Our proteomic data revealed that PRDX1 was overexpressed in unilateral varicocele compared to bilateral varicocele." (PMID 32365753, 2020). "Some of the DEP in unilateral varicocele group including PRDX1, SOD1, SOD2 were shown to be involved in the removal of superoxide." (PMID 25890347, 2015). "In terms of PRDXs expression in spermatozoa, the population of infertile men is heterogeneous; sperm PRDX6 was low in 67% and 39% varicocele and idiopathic infertile patients, respectively, whereas sperm PRDX1 was only low in 42% of varicocele patients." (PMID 25780579, 2014). "Hence, the acetylation state of PRDX1 is critical in varicocele patients with oxidative stress-mediated infertility." (PMID 32365753, 2020). "In addition, the acetylation status of proteins, such as HIST1H2B, PRDX1, SDHA, and SOD1, can serve as a biomarker for PTM defects pertaining to the acetylation process in the ejaculated spermatozoa of varicocele patients." (PMID 32365753, 2020). "PRDX6, but not PRDX1, is present in low amounts in seminal plasma of infertile men with clinical varicocele." (PMID 25780579, 2014). "The total quantity of PRDX1 and PRDX6, but not for PRDX4 and PRDX5, is lower in spermatozoa from varicocele patients (prior to surgery) than in idiopathic infertile men or healthy donors." (PMID 25780579, 2014).
diabetes (5 papers, 2018 to 2024). "At present, diabetes caused a significant down-regulation of Nrf2 and downstream molecules such as NQO-1 and Prdx-1, and CVB-D alleviated the expression of these proteins both in vivo and in vitro." (PMID 32286474, 2020). "Next, we evaluated HDAC6 activity, total Prdx1 levels, and acetylated-Prdx1 levels in diabetic and nondiabetic rats to explore the underlying mechanism of aggravated MI/R injury in diabetes." (PMID 30046381, 2018). "Again, the levels of PRDX1 were significantly decreased in PD cases and a coinciding ICD-10 code for insulin-dependent diabetes mellitus." (PMID 39371139, 2024). "Deficiencies in antioxidant defenses against ROS described in diabetes included antioxidant enzyme such as SOD1, PRDX1, Hmox1 and antioxidants, thioredoxin 1 (Txn1)." (PMID 37337262, 2023).
infertile (5 papers, 2014 to 2025). "PRDX1 is a thiol-specific antioxidant enzyme that is essential for protecting sperm from oxidative stress, with reduced levels being linked to infertility." (PMID 40649876, 2025). "Date palm pollen has been shown to improve semen quality and enhance PRDX1 expression in infertile men." (PMID 40649876, 2025). "Although seminal plasma and all subcellular sperm compartments contain PRDXs, ensuring an effective first-line defense against ROS, spermatozoa from infertile men display lower amounts of PRDX1 and PRDX6 with a relatively high degree of thiol oxidation." (PMID 33924936, 2021). "Although PRDXs are largely distributed in seminal plasma as well as in all subcellular sperm compartments, spermatozoa from infertile men exhibit lower amounts of PRDX1 and PRDX6 with a relatively high degree of thiol oxidation which inhibits PRDX activities." (PMID 33924936, 2021).
Insulin resistance (5 papers, 2018 to 2024). Increased resistance towards insulin, that is, diminished effectiveness of insulin in reducing blood glucose levels. "At present, two studies have reported an increase in Prdx1 in T2DM was positively correlated with the homeostasis model assessment of insulin resistance (HOMA-IR) (r = 0.276, p< 0.01)." (PMID 36619535, 2022). "As well as other proteins, such as 60 kDa heat shock protein, peroxiredoxin-1, pyruvate carboxylase and regucalcin; they have been found increased in different models of insulin resistance." (PMID 29857581, 2018).
ischemic stroke (5 papers, 2021 to 2024). A stroke disorder caused by obstruction of blood flow to the brain, due to thrombotic (local blood clot formation) or embolic (due to a blood clot or other material traveling from another site) event. "The causal relationship between PRDX1-related methylation sites (cg02631906 and cg08483560) and the risk of ischemic stroke further validates PRDX1 as a crucial target." (PMID 39595569, 2024). "Colocalization analysis identified PRDX1 and ischemic stroke as sharing the causal variant rs17522918, which has important implications for understanding the disease’s pathogenesis and developing targeted interventions." (PMID 39595569, 2024). "The study also highlights the causal effects of PRDX1-related methylation sites (cg02631906 and cg08483560) on ischemic stroke, emphasizing their increased role in the risk of the condition." (PMID 39595569, 2024). "Colocalization analysis can help identify shared causal SNPs associated with both PRDX1 and ischemic stroke." (PMID 39595569, 2024). "PRDX1 is identified as a key target in ischemic stroke based on colocalization analysis, which revealed that PRDX1 and ischemic stroke share the causal variant rs17522918." (PMID 39595569, 2024). "The study found that two methylation sites (cg02631906 and cg08483560) associated with the PRDX1 gene were significantly linked to the risk of ischemic stroke and showed a causal relationship." (PMID 39595569, 2024). "Two methylation sites associated with the PRDX1 gene (cg02631906 and cg08483560) remained significant under the MR Hypothesis and were identified as cause-and-effect associated with ischemic stroke according to the IVW method." (PMID 39595569, 2024). "The deficiency of PRDX1 exacerbated microglial cell death and brain damage in ischemic stroke." (PMID 39796134, 2024). "Our analysis demonstrated significant upregulation of PRDX1 in the ischemic stroke model, with modulation by IPostC, underscoring its potential as a therapeutic target." (PMID 39595569, 2024). "It was also found that the peroxiredoxin-1 expression in patients with ischemic stroke is 10 times higher than in healthy people." (PMID 34948066, 2021). "PRDX1 and nine ischemic strokes were found to be rs17522918 in all GWAS colocalization analyses." (PMID 39595569, 2024). "To observe the changes in the four biomarkers CDKN1A, GPX4, PRDX1, and PRDX6 in patients with ischemic stroke, we measured their expression of these four biomarkers in peripheral blood using RT-PCR." (PMID 38360841, 2024). "The results showed that CDKN1A, PRDX1, and PRDX6 expression levels were significantly increased, which was consistent with our study, suggesting that CDKN1A, PRDX1, and PRDX6 may be involved in the occurrence and development of ischemic stroke." (PMID 38360841, 2024).
oral cancer (5 papers, 2014 to 2023). "PRDX1 was overexpressed in oral leukoplakia and oral cancers, and associated with local recurrence, which may be clinically useful in guiding treatment for HNSCC patients." (PMID 31429766, 2019). "In oral cancer, PRDX1 is highly expressed and is significantly correlated with tumor staging, lymph node metastasis, and pathological grading, making it a promising biomarker for predicting lymph node metastasis and prognosis in oral cancer patients." (PMID 37781072, 2023).